UCA1 (urothelial cancer associated 1)
Diseases named in the same sentence as UCA1 in open-access papers (continued):
Sharing a sentence is not in itself a finding about the gene and the disease.
cancer (continued). "The lncRNA, urothelial carcinoma-associated 1 (UCA1) has been identified as an oncogene that enhances cell proliferation, inhibits apoptosis and promotes cell cycle progression in several types of cancer." (PMID 30940776, 2019). "The lncRNA UCA1 has been found to reactive and is a promising diagnostic and prognostic biomarker in various malignant tumors." (PMID 30377411, 2018). "Considering the oncogenic role of UCA1 and that the alteration metabolism is associated with the abnormal proliferation of cancer cells, we analyzed the effect of UCA1 on glycolysis in NSCLC cells by measuring the glucose consumption and lactate production." (PMID 35540445, 2018). "In the study of the mechanism of this effect, we found that BMP9 can increase the expression of lncRNA UCA1 (Urothelial cancer associated 1) through phosphorylated AKT." (PMID 29642505, 2018). "In many cancers, the key role of the long noncoding RNA (lncRNA) urothelial carcinoma-associated 1 (UCA1) in anticancer drug resistance has been confirmed." (PMID 30377411, 2018). "The lncRNA, urothelial cancer-associated 1 (UCA1) was identified as a common molecular marker for lymph node metastasis and prognosis in various cancers." (PMID 28410241, 2017). "Recently, the aberrant expression of urothelial carcinoma associated 1 (UCA1) was observed in many types of cancers." (PMID 29221199, 2017). "LncRNA UCA1 expression is associated with a number of anti-cancer drug resistance tumors, however, the mechanisms remain to be elucidated in greater detail, especially from a clinical standpoint." (PMID 28969100, 2017). "The meta-analysis showed that higher expression of lncRNA UCA1 (HR = 1.71, 95% CI: 1.43–1.99) was associated with poor OS based on cancer type, cut-off value, analysis type and sample size." (PMID 28969100, 2017). "We provide evidence that KSHV deregulates hundreds of host lncRNAs including many cancer-associated lncRNAs such as UCA1, ANRIL and MEG3 in both a miRNA dependent and independent manner." (PMID 28715488, 2017). "Urothelial carcinoma associated 1 (UCA1) has been involved in anti-cancer drug resistance in several tumors." (PMID 29033906, 2017). "Yet, lncRNA UCA1 shows great potential as a diagnostic, predictive or prognostic biomarker, and a therapeutic target in malignant tumors." (PMID 28969100, 2017). "The long non-coding RNA (lncRNA) urothelial carcinoma-associated 1 (UCA1) has been recently shown to be dysregulated during disease occurrence and to play an important role in the progression of several cancers." (PMID 29212166, 2017). "Cancer-upregulated drug resistant (CUDR) or urothelial cancer-associated 1 (UCA1) is an independent prognostic biomarker highly expressing in various human tumors and involved in tumorigenesis." (PMID 28872613, 2017). "The pivotal role of the long non-coding RNA (lncRNA) urothelial carcinoma associated 1 (UCA1) in anti-cancer drug resistance has been confirmed in many cancers." (PMID 28969100, 2017). "Uca1 (urothelial cancer associated 1) is a lncRNA that plays a central role in bladder cancer growth, progression and invasion." (PMID 29206174, 2017). "Urothelial cancer associated 1 also known as UCA1 is located on 19p13.12 encodes 3 isoforms (1.4, 2.2 and 2.7 kb) with ployA tails, in which the 2.2 kb isoform is called cancer upregulated drug resistant (CUDR)." (PMID 28423704, 2017). "Urothelial carcinoma associated 1 (UCA1) is a recently identified lncRNA with aberrant expression in various types of cancer." (PMID 27902466, 2017). "Urothelial carcinoma associated 1 (UCA1), an lncRNA, had been reported for its overexpression and oncogenic effect on various human cancers." (PMID 28624787, 2017). "Long non‐coding RNA urothelial cancer associated 1 (UCA1) is generally regarded as an oncogene in some cancers." (PMID 29125238, 2017).
cancer (continued). "In this meta-analysis, we qualified and evaluated present studies to explore the association of UCA1 with prognostic and clinicopathological significance in patients with different types of carcinomas." (PMID 28423704, 2017). "The strength of association between UCA1 and cancer prognosis was assessed by computing the hazard ratio (HR) with its corresponding 95% confidence interval (CI)." (PMID 27329842, 2016). "Recently, lncRNA urothelial carcinoma-associated 1 (UCA1) has attracted great attention due to its involvement in diverse cancers." (PMID 28074092, 2016). "This is the first meta-analysis to evaluate the association between UCA1 levels and cancer prognosis." (PMID 27329842, 2016). "High expression of UCA1 was reported to be associated with unfavorable prognosis in cancer patients." (PMID 27517147, 2016). "UCA1 was involved in cancer progression, and its aberrant expression was associated with a broad range of cellular processes, including cell cycle distribution, apoptosis and proliferation." (PMID 27517147, 2016). "Although the association between UCA1 expression and cancer progression was a particular concern for these studies, these results were limited by small sample sizes or inconsistent conclusions." (PMID 28074092, 2016). "This meta-analysis investigated an association between UCA1 levels and survival times of cancer patients." (PMID 27329842, 2016). "No meta-analysis was been conducted to assess the association between UCA1 and the survival of patients with cancers." (PMID 27329842, 2016). "Well-designed studies with large sample sizes are needed to confirm further the association between UCA1 and clinical outcomes of cancers in various ethnic populations." (PMID 27329842, 2016). "The long non-coding RNA (lncRNA) urothelial carcinoma-associated 1 (UCA1) has been recently shown to be dysregulated, which plays an important role in the progression of several cancers." (PMID 25760077, 2015). "The aim of this study was to explore the role of long non-coding RNA UCA1 (urothelial cancer-associated 1) in acquired resistance to epidermal growth factor receptor tyrosine kinase inhibitors (EGFR-TKIs) in EGFR-mutant non-small cell lung cancer (NSCLC)." (PMID 26160838, 2015). "Cancer up-regulated drug resistant (Urothelial cancer associated 1, UCA1, CUDR) is a novel non-coding RNA gene, which plays a pivotal role in cancer progression." (PMID 26513297, 2015). "Recent data demonstrated that hnRNP I can also form a functional ribonucleoprotein complex with UCA1 (urothelial carcinoma-associated 1) and increase UCA1 stability." (PMID 26448935, 2015). "The overexpression of UCA1 is linked to resistance to chemotherapeutic agents like cisplatin and gemcitabine, and targeting UCA1 through knockdown strategies has been shown to restore drug sensitivity in resistant cancer cells." (PMID 40149330, 2025). "Despite the accumulating evidence suggesting that overexpression of UCA1 in certain cancer entities can modulate tumorigenesis, the underlying molecular mechanisms regarding the regulatory roles of UCA1 in GC are still unknown." (PMID 38534790, 2024). "UCA1 was the first known cancer-causing long non-coding RNA and is greatly overexpressed in BC." (PMID 38398192, 2024). "Urothelial cancer associated 1 (UCA1) is one lncRNA upregulated in various cancers." (PMID 38226210, 2024). "The lncRNA UCA1 knockdown caused cancer regression and might potentially be employed for therapeutic interventions." (PMID 37245177, 2023). "For example, urothelial cancer-associated 1 (UCA1) is a lincRNA with a length of 1,400 nt." (PMID 36203765, 2022). "Furthermore, it has been demonstrated that higher levels of UCA1 are associated with shorter OS and increased lymph node metastasis in multiple human cancers." (PMID 34527584, 2021). "Urothelial cancer associated-1 (UCA1) was identified as an oncogene in various cancers." (PMID 32943997, 2020).
cancer (continued). "This rule might also be applicable to lncRNA UCA1, which suggested that certain SNPs of UCA1 counted in regulating cancer (e.g. CRC) risk by interfering with binding of UCA1 to miRNAs." (PMID 32143722, 2020). "UCA1 (urothelial carcinoma associated 1) is a lncRNA that was first identified in human bladder carcinoma, whose expression is found to be up-regulated in many other cancers till now." (PMID 31272462, 2019). "The UCA1/mTOR axis is suggested to be induced by cancer-associated fibroblasts (CAFs)." (PMID 31480503, 2019). "The UCA1 gene encodes 3 exons located on chromosome 19 and it is highly expressed in cancer cells." (PMID 30441811, 2018). "lncRNA urothelial cancer-associated 1 (UCA1) is involved in cancer invasion and metastasis." (PMID 27802187, 2017). "Moreover, growing subsequent evidence suggests that the aberrant overexpression of UCA1 is associated with high risk of poor outcome or clinicopathological features in several types of cancer, including BC." (PMID 29165379, 2017). "It has been demonstrated that hsa-miR-145 inhibits BC cell migration and invasion; consequently, the overexpression of UCA1 is linked to marked repression of hsa-miR-145, and vice versa, resulting in a stimulus that may make cancer more aggressive." (PMID 29165379, 2017). "A total of 19/16 studies with 1587/1291 cancer patients were included to evaluate the association between UCA1 expression and overall survival (OS) and clinicopathological factors of malignancies by computing hazard ratio (HR), odds ratios (OR) and confidence interval (CI)." (PMID 28423704, 2017). "In conclusion, the present analysis showed that overexpression of UCA1 might predict a poor prognosis in various types of malignancies, especially in Chinese population and was associated with poor cancer stage and positive lymphatic metastasis." (PMID 28423704, 2017). "However, the diagnostic value of lncRNA UCA1 in body fluid samples for other types of malignant tumors remains to be confirmed." (PMID 28969100, 2017). "Importantly, UCA1 has been considered as a promising diagnostic marker and potential therapeutic target for human cancers." (PMID 27517147, 2016). "Therefore, this meta-analysis investigated an association between UCA1 and the survival of cancer patients." (PMID 27329842, 2016). "Furthermore, the upregulation of the lncRNAs long stress-induced non-coding transcript 5 (LSINCT5), colon cancer-associated transcript 2 (CCAT2), competing endogenous lncRNA 2 (CERNA2), PVT1, and urothelial cancer-associated 1 (UCA1) have also been implicated in cancer-promoting mechanisms of OC." (PMID 34404407, 2021). "Interestingly, linc00152 and UCA1 have previously been linked with cancers by others." (PMID 32733618, 2020). "On the other hand, HOTAIR and UCA1 play significant roles in cancer development and progression, primarily through epigenetic mechanisms like miRNA sponging or by recruiting specific chromatin remodelers." (PMID 38279264, 2024). "The Hippo–YAP signalling pathway, which is activated by the SE‐lncRNA UCA1, has been shown to promote angiogenesis in several cancer types, including pancreatic ductal adenocarcinoma (PDAC) and EOC, through multiple mechanisms." (PMID 39690143, 2024). "Through the mTOR/STAT3 pathway and the miR143/HK2 axis, UCA1 also boosts glucose metabolism in cancer cells." (PMID 38398192, 2024). "UCA1 serves a variety of biological roles in cancer cells, including promoting cell proliferation and transformation, increasing invasion and mortality, and causing treatment resistance in cancer cells." (PMID 38294554, 2024). "For the prognostic value of UCA1 in cancer tissues, the conclusions of current studies were relatively consistent." (PMID 37564930, 2023). "A qRT-PCR analysis of the expression of 17 lncRNAs in the serum exosomes of cancer subjects demonstrated a downregulation of lncRNA UCA1 in exosomes from the serum samples of patients, while lncRNA TUG1 was overexpressed." (PMID 37569782, 2023).
cancer (continued). "Bioinformatic analysis with small sample validation suggested the higher expression level of UCA1 in cancer tissues than in adjacent tissues." (PMID 37564930, 2023). "The combined ROC curve of TUG1:UCA1 demonstrated high effectivity for the discrimination of subjects with cancer from healthy ones." (PMID 37569782, 2023). "UCA1 participated in the regulation of the key of PaC progression, including cancer cell growth, invasion, migration, metastasis and angiogenesis." (PMID 36741256, 2023). "In detail, UCA1 overexpression promoted the proliferation, migration, and invasion of cancer cells, by activating the Wnt/β-catenin signaling pathway." (PMID 35406495, 2022). "In our study, MIR4435-1HG and UCA1 were identified to exhibit cancer-promoting activity, while the clinical effect of RP11-617F23.1 was contradictory." (PMID 35794986, 2022). "In pancreatic cancer, the exosomal lncRNA UCA1 secreted from cancer cells under hypoxic conditions was shown to promote angiogenesis via a miR-96-5p/AMOTL2/ERK1/2 pathway." (PMID 36176760, 2022). "Using PSA ≥4 and UCA1 score ≥−3.47, 122 cancer patients were accurately diagnosed with a sensitivity of 0.992, while 102 prostate biopsies (22.42%) were excluded." (PMID 35289508, 2022). "Further, it was found that cancer cells can gain metastatic potential following treatment with serum exosomes harboring UCA1." (PMID 35055115, 2022). "In all patients of two cohort (n = 897), the UCA1 score was superior to PSA only for detection of clinically significant cancer (28% VS." (PMID 35289508, 2022). "Of note, certain lncRNAs including UCA1 can interact with a variety of miRNAs which subsequently alter gene expression profiles and control cancer progression." (PMID 35901079, 2022). "In bladder cancer, the lncRNA (UCA1) preferentially secreted by hypoxic cancer cells was shown to promote cancer growth by stimulating EMT both in vitro and in vivo." (PMID 36176760, 2022). "Urothelial Cancer Associated 1 (UCA1) is a super-enhancer derived eRNA expressed in the early embryo development, but also expressed in cancer." (PMID 35454885, 2022). "Using PSA ≥4 and UCA1 score ≥−3.47, 122 cancer cases were accurately detected in 455 patients with a sensitivity of 0.992 (only one cancer patient was missed) and a specificity of 0.294." (PMID 35289508, 2022). "Because the lower boundary of the two‐sided 95% CI was greater than 0 percentage points, the UCA1 score was deemed superior to PSA only for detection of clinically significant cancer (p = 0.007)." (PMID 35289508, 2022). "For instance, lncRNAs such as UCA1 and HOTTIP have been implicated to play a promising role in carcinogenesis, cancer progression, and chemoresistance." (PMID 35586209, 2022). "Our study suggest that UCA1 is an important substrate for m6A, upregulation of UCA1 by m6A-modification promotes UCA1-mediated cancer cell proliferation and survival." (PMID 34809621, 2021). "It has been confirmed that the CAPERα/TBX3 complex directly inhibits UCA1 transcription and promotes cancer cell senescence by regulating chromatin structure." (PMID 33777227, 2021). "Recent researches have pointed out that UCA1 act as a miRNA sponge and participate in the regulation of chemo-resistance in diversified cancers." (PMID 33969374, 2021). "UCA1 promotes the development of cancer cells by activating the JAK/STAT signaling pathway, including multiple myeloma (MM), AML and pre-eclampsia." (PMID 33777227, 2021). "Extensive studies regarding the role of UCA1 in cancers have uncovered that UCA1 promotes cancer development by various mechanisms." (PMID 34809621, 2021). "Targeted knockout of UCA1 can be used to improve radiosensitivity, inhibit cancer metastasis, prevent cancer growth in vivo, promote apoptosis and reverse drug resistance of cancer cells." (PMID 33777227, 2021). "UCA1 is frequently upregulated in a variety of cancers, including CRC, and it can play an oncogenic role by various mechanisms." (PMID 34809621, 2021).
cancer (continued). "Accumulating researches have shown that UCA1 is dysregulated in a variety of cancer tissues and cells." (PMID 34345210, 2021). "UCA1 is increased in various cancers and promotes processes such as proliferation, migration and immune escape, and inhibits apoptosis." (PMID 33923632, 2021). "LncRNA UCA1 has gained attention in recent years because of its oncogenic effect in many cancers, including GC." (PMID 34238213, 2021). "Accumulated studies have proved that UCA1 is connected with the chemo-resistance of various cancers." (PMID 33969374, 2021). "Abnormal expression of UCA1 is reported to be related to the occurrence and development of various cancers." (PMID 34233576, 2021). "Among them, lncRNAs PVT1, H19, and UCA1 were proved to involve in gemcitabine resistance in other cancers and CCA progression, suggested that our screen strategy for gemcitabine resistance-related lncRNAs were feasible." (PMID 33436545, 2021). "In bladder cancer, hypoxia induces upregulation of lncRNA UCA1 in both cancer cell line and TEX, promoting cancer cell migration and invasion." (PMID 33808190, 2021). "Further studies have shown that UCA1 is highly expressed and exerts oncogenic activity in numerous cancers, such as gastric cancer, colorectal cancer, liver cancer, breast cancer, cervical cancer, and prostate cancer." (PMID 34760707, 2021). "Among lncRNAs, lncRNA UCA1 has been demonstrated to have significant regulatory roles in cancer progression, including cell proliferation, invasion, migration and metastasis, and chemoresistance in BLS-211 BC cells." (PMID 33936199, 2021). "Given that UCA1 plays an oncogenic role in a variety of cancer, these findings support the importance of m6A-mediated UCA1 expression." (PMID 34809621, 2021). "Previous research has illustrated that UCA1 positively regulates chemo‐resistance in several types of cancers." (PMID 33565716, 2021). "We applied the TIMER2 approach to analyze the expression status of UCA1 across various types of cancer of the TCGA data." (PMID 34238213, 2021). "According to previous reports, UCA1 induces chemo‐resistance mainly through the activation of cellular signaling pathways which confers cancer cells’ abilities to adapt to harsh environments with chemo‐reagents." (PMID 33565716, 2021). "BMP9 or TGF-β can upregulate UCA1 expression to promote invasion and metastasis of cancer cells, including BC and GC cells." (PMID 33777227, 2021). "UCA1 has been shown to facilitate the cancer cell growth, migration, invasion, metastasis and drug resistance by activating PI3K/AKT, mTOR/STAT3, and other signaling pathways." (PMID 33565716, 2021). "In conclusion, lncRNA UCA1 has been identified as a novel and potential molecular target for GI cancer in the last decade based on its potent regulatory roles in cancer progression and chemoresistance." (PMID 33936199, 2021). "This study shows that CAFs promote the cisplatin resistance of cancer cells via exosomal UCA1 transport." (PMID 33050576, 2020). "LncRNA UCA1 was found to be aberrantly expressed in various cancer tissues and multiple studies indicated that UCA1 worked as an oncogene in cancers." (PMID 32943997, 2020). "The results showed that GAS8-AS1 was significantly downregulated (p < 0.05), while UCA1 was significantly upregulated (p < 0.05) in OS tissues in comparison to adjacent non-cancer tissues of OS patients." (PMID 32013985, 2020). "UCA1 can also interact with microRNAs(miRNAs), a type of regulatory ncRNA to compete endogenous RNA in cancer cells." (PMID 33680939, 2020). "UCA1 endowed cancer cells with resistance to cisplatin by functioning as a miRNA sponge against miR-103a which targets WEE1, a cell-cycle kinase regulating G2-M checkpoint." (PMID 33050576, 2020). "It is known that UCA1 can participate in cancer biology by interacting with multiple signaling pathways, such as the FGFR1/ERK signaling pathway and the TGF-β pathway." (PMID 32013985, 2020).